CARM1 (coactivator associated arginine methyltransferase 1)
Diseases named in the same sentence as CARM1 in open-access papers (continued):
Sharing a sentence is not in itself a finding about the gene and the disease.
tumor (continued). "Consistently, immunofluorescence assay also confirmed the significantly suppressed CARM1 level in ADM-treated tumor cells, and SA-β-gal assay also indicated that ADM-induced cell senescence could be notably reversed by the overexpression of CRRM1." (PMID 35593475, 2022). "Importantly, treatment with a CARM1 inhibitor rescued the tumor-promoting effects of CARM1 both in vitro and in vivo." (PMID 35246137, 2022). "Overall, the inhibition of the activity against CARM1 suppresses tumor progression, promotes T-cell infiltration and sustained immune memory, and may be an effective for immunotherapy of drug-resistant tumors." (PMID 36713412, 2022). "In conclusion, these observations altogether suggest that CARM1 could promote NSCLC cell proliferation and colony-formation in vitro, demonstrating the tumor-promoting role of CARM1 in NSCLC." (PMID 32487779, 2020). "Taken together, it is reasonable to conclude that CARM1 functions as either tumor-promoting or anti-proliferative functions, suggesting that the actions of CARM1 might depend on the cellular context and tumor type." (PMID 32487779, 2020). "CARM1 was immunocytochemically distributed in both cytoplasm and nuclei of tumor cells." (PMID 32487779, 2020). "For example, SMARCA4-CARM1 is an interaction captured only in the Finnish cohort (the tumour-suppressive gene CARM1, interacts with a gene associated with abnormal LDL-C levels and required for tumour cell growth, SMARCA4)." (PMID 31070705, 2019). "Mechanistically, CARM1 promotes EZH2-mediated silencing of target tumor suppressor genes." (PMID 29434212, 2018). "This suggests there are distinct functions of CARM1 among molecular tumor types." (PMID 23663560, 2013). "Along with its involvement in transcription regulation, pre-mRNA splicing, and the cell cycle, CARM1 plays various roles in different cellular processes, including DNA end resection, the replication stress response, cell autophagy, tumor immunity, and tumor metabolism." (PMID 40016178, 2025). "Our exploration extends beyond CARM1’s initial characterization as a transcriptional coactivator, revealing its critical involvement in diverse physiological processes, such as oxidative stress, cell death, and metabolism, contributing to tumor development, metastasis, and therapeutic resistance." (PMID 38619752, 2024). "Furthermore, the roles of molecules such as Coactivator Associated Arginine Methyltransferase 1 (CARM1)and heat shock protein family B (small) member 1 (HSPB1) in regulating ferroptosis further emphasize the importance of ferroptosis in the tumor immune microenvironment." (PMID 39273090, 2024). "Thus, we concluded that targeting CARM1 could be a potential therapeutic strategy for tumor ferroptosis." (PMID 37946697, 2023). "Moreover, elevated circHMGB2 was identified to upregulate the expression of the downstream molecule CARM1 by sponging miR-181a-5p, which indicated that high level of circHMGB2 could reset the tumor immune microenvironment by CARM1." (PMID 35525959, 2022). "The variations of CARM1 expression in T lymphocytes and tumor cells are still unknown." (PMID 34745258, 2021). "Regardless, directly targeting CARM1 may have unintended tumor-promoting effects." (PMID 29434212, 2018). "However, the predominance of which pathway is regulated by CARM1 depends on the tumor phenotype." (PMID 23915145, 2013). "To summarize, these findings showed that CARM1 promoted HCC cell migration and invasion in vitro, as well as tumor metastasis in vivo." (PMID 40016178, 2025). "CARM1, for example, induced the methylation of BAF155, downregulating the expression of EZH2/BAF155 target tumor suppressor genes." (PMID 39678497, 2024). "Glucose starvation raises CARM1 protein levels, which inhibits the catalytic activity of GAPDH for glycolysis by methylating R234, slowing tumor cell proliferation." (PMID 38619752, 2024).
tumor (continued). "We further tested the effect of CARM1 and GATAD2A on tumor growth in vivo by injecting nude mice subcutaneously with control MCF7 cells or cells infected with shRNA targeting CARM1 or GATAD2A, and then treated with estrogen to stimulate tumor growth." (PMID 38676947, 2024). "CARM1 cooperates with HIF1A to occupy the promoters of CDK4, Cyclin D1, β-Catenin, HIF1A, MALAT1, and SIX1 and promote tumor progression in TNBC." (PMID 38476024, 2024). "To gain a molecular understanding of the NFIB/CARM1 pathway, we perform ATAC-seq and RNA-seq on the same tumor biopsies obtained for TKO, TKO;NfibR388K and TKO;Carm1KO mutant mice." (PMID 36690626, 2023). "Recent studies suggest that accumulation of saturated FAs contributes to the tumor suppressive effects of SCD1 inhibition, which predicts that CARM1 expression will increase the tolerance to saturated FAs." (PMID 37377614, 2023). "CARM1 (also known as PRMT4) catalyzes the formation of asymmetric dimethylarginine (me2a) and facilitates tumor progression through a variety of methods." (PMID 37946697, 2023). "Some studies have confirmed the involvement of CARM1 in the pathogenesis of MM, and its selective inhibitors (e.g., EZM2302, TP064) have been shown to inhibit the tumor cell activity of MM." (PMID 37477799, 2023). "CARM1, an epigenetic enzyme identified by CRISPR screening, exerts a dual role on both tumor cells and cytotoxic T cells to impede anti-tumor immune response." (PMID 37964355, 2023). "The same study also found that CARM1 inhibition enhances the antitumor functions of CD8 T cells and promotes the maintenance of tumor-infiltrating T cells that express memory markers." (PMID 37536629, 2023). "In summary, we found and provided evidence that CARM1 inhibited ferroptosis, which is closely related to ACSL4 R339 methylation, and that its inhibitor suppressed tumor progression when combined with anti‐PD‐1." (PMID 37946697, 2023). "This discovery suggests that CARM1‐mediated ACSL4 R339 methylation is a vital regulatory mechanism for ferroptosis resistance and tumor progression." (PMID 37946697, 2023). "Moreover, it is eye-catching that CARM1-KO T cells exert more effective antitumor effects than wild-type, indicating that CARM1 inhibition enables immunotherapy of resistant tumors by dual effects on tumor cells and T cells, which has great clinical translational value." (PMID 35033016, 2022). "The overexpression of CARM1 was reported to have a role in MM; a potent CARM1 inhibitor, namely, EZM2302, significantly inhibited the growth of MM tumour." (PMID 36359286, 2022). "MiR-424-5p can inhibit tumor proliferation and migration by targeting certain genes (WEE1, E2F7, KIF23, MIEF2, CARM1, Notch) or regulating protein expression." (PMID 35409396, 2022). "Distinct from CARM1, PRMT5 inhibition suppressed the induction of tumor antigen-specific CD8+ T cells in vitro." (PMID 35493527, 2022). "Our study provided evidence that CDKN2AIP exhibits cell senescence-inducing function by suppressing CARM1, which further expands the regulatory molecular network of CDKN2AIP on tumor cell senescence." (PMID 35593475, 2022). "CDKN2AIP functions as tumor suppressor through two diverse routes: on one hand, CDKN2AIP induces cell senescence by interacting with CARM1, and on the other hand, CDKN2AIP also induces apoptosis by interacting with eIF4β and reduces eIF4β phosphorylation." (PMID 35593475, 2022). "Previous study has found that the expression of most PRMTs in primary tumours and metastases remains unchanged compared with normal melanocytes, and only PRMT4/CARM1 was significantly induced during tumor development." (PMID 35311114, 2022). "Overexpression of CARM1 induced hyper-branching of the mammary glands, increased Ki-67 staining, and augmented HER2-oncogene-induced tumor formation in mouse models." (PMID 34865122, 2021). "In order to understand the role of CARM1 and YY1 in tumor growth in vivo, xenograft studies were performed in NSG (NOD-SCID gamma) mice." (PMID 31217904, 2019).
tumor (continued). "Our data demonstrate a dependence of CARM1-expressing cells on EZH2 activity, reflecting the silencing of EZH2 target tumor suppressor genes in a CARM1-dependent manner." (PMID 29434212, 2018). "These and our findings that enzyme activities of CARM1/PRMT4 and PRMT6 are capable of regulating tumor suppressor activity and cellular proliferation raise questions of a common meaning for cellular metabolism." (PMID 22916108, 2012). "In tumor and non-muscle cell models, CARM1 typically functions as a direct modifier of metabolic enzymes, dynamically regulating enzyme activity through post-translational modifications, yet its effects demonstrate high heterogeneity." (PMID 41488004, 2025). "Consequently, CARM1 shifts the metabolism balance from OXPHOS to aerobic glycolysis, fostering tumor cell proliferation, migration and metastasis." (PMID 38619752, 2024). "Indeed, EZM2302, a CARM1-specific inhibitor, inhibits CARM1-mediated GATAD2A methylation, GATAD2A chromatin binding, transcriptional activation of cell cycle genes, cell cycle progression, and eventually tumor growth." (PMID 38676947, 2024). "Tumor volume was dramatically impaired when CARM1 was ablated, and this phenotype was not rescued when the KO cells were complemented with mutant CARM1." (PMID 36690626, 2023). "In addition, we defined the level of CARM1 expression according to the immunohistochemical score of CARM1 and found that the expression of CARM1 was significantly negatively correlated with lipid ROS and MDA levels in CRC tumor tissues of patients." (PMID 37946697, 2023). "Pharmacological inhibition of CARM1 and BAF155 methylation not only abrogated the expression of an array of oncogenes, but also boosted host immune responses by enhancing the activity and tumor infiltration of cytotoxic T cells." (PMID 34865122, 2021). "As a control, B-I09 did not significantly reduce the tumor burden in the orthotopic model established by CARM1 knockout A1847 cells." (PMID 34493732, 2021). "Therefore, EZH2 inhibition reactivates the tumor suppressive BAF155/EZH2 target genes to promote apoptosis and inhibit proliferation of CARM1-expressing cells." (PMID 29434212, 2018). "When data were stratified for multivariate analysis, only residual tumor remained significant (P = 0.0002) for shorter progression-free survival, but residual tumor (≥1 cm) and high NAC1/CARM1 expression remained significant (P = 0.0027 and P = 0.0418, respectively) for overall survival." (PMID 29983869, 2018). "Specifically, we observe significantly higher levels of cyt-CARM1 in the African race group, independent of tumor categories, relative to the higher levels of nuc-CARM1 in Afr." (PMID 23663560, 2013). "Most tumor sections show an apparent nuclear exclusion of CARM1 in the African samples (data not shown)." (PMID 23663560, 2013). "Although the SWI/SNF complex is a well-established tumor suppressor and it may seem counter-intuitive to inhibit CARM1 activity in this context, it is not." (PMID 37536629, 2023). "Likewise, B-I09 significantly reduced the tumor burden in CARM1-high, but not in CARM1-low, HGSOC patient-derived xenograft (PDX) models." (PMID 34493732, 2021). "However, silencing of CARM1 did not result in as much change in tumor size as was seen with YY1 knock-down." (PMID 31217904, 2019). "CARM1 or PRKACA KD led to a significantly smaller volume and lighter weight of tumor tissues compared with the negative control." (PMID 38201567, 2023). "By H score analysis, the expression of both CARM1 and CCNE2 were profoundly elevated in the NSCLC tumor tissues when compared with that in the adjacent non-tumor tissues (n =20, **P < 0.01)." (PMID 32487779, 2020). "Unlike CARM1, CCNE2 was preferentially in the nuclei of tumor cells." (PMID 32487779, 2020).
adenocarcinoma (3 papers, 2013 to 2023). A common cancer characterized by the presence of malignant glandular cells. "Through the Kaplan-Meier plotter database, we found that high expression of CARM1 or CCNE2 was highly associated with shorter 10-year overall survival of NSCLC (adenocarcinoma) patients, implying the oncogenic roles of CARM1 and CCNE2 in promoting the progression of NSCLC." (PMID 32487779, 2020). "Notably, high expression of CARM1 (Cutoff value was 262; P < 0.01) or CCNE2 (Cutoff value was 228; P < 0.01) was highly associated with shorter 10-year overall survival of NSCLC (adenocarcinoma) patients, implying the oncogenic roles of CARM1 and CCNE2 in promoting the progression of NSCLC." (PMID 32487779, 2020). "Subsequently, publicly available CRC expression profiles in TCGA‐COAD and GSE20916 datasets were analyzed, and CARM1 expression was elevated in both primary tumors and adenocarcinomas." (PMID 37946697, 2023). "Staining for CARM1 was significantly stronger in adenocarcinoma compared with adjacent benign epithelium." (PMID 23915145, 2013).
hematologic malignancies (3 papers, 2022 to 2024). "Coactivator-associated arginine methyltransferase 1 (CARM1) is an important target in hematologic malignancies." (PMID 38649367, 2024). "Given its substrate targets (e.g. BAF155 and RUNX1) and gene targets (e.g. BMI-1 and ID2), CARM1 and phospho-CARM1 appear to play a pivotal role in hematologic malignancies with the JAK2-V617F mutation, and likely in other settings as well." (PMID 38649367, 2024). "Inhibitors directed against PRMTs type I, i.e., PRMT1, CARM1, PRMT5, and PRMT7, have been tested on hematological malignancy models and have shown a significant decrease in malignant cell proliferation and an increased apoptosis." (PMID 36358861, 2022).
metabolic disease (2 papers, 2025). A congenital disorder (due to inherited enzyme abnormality) or acquired (due to failure of a metabolically important organ) disorder resulting from an abnormal metabolic process. "In the realm of metabolic diseases, CARM1's significance has become increasingly apparent." (PMID 39922487, 2025).
neurodegenerative disease (2 papers, 2020 to 2023). A disorder of the central nervous system characterized by gradual and progressive loss of neural tissue and neurologic function. "Consistent with our finding, a previous study reported a role of CARM1 in promoting FA de novo synthesis in neurodegenerative diseases by upregulating ACC mRNA at the transcription level." (PMID 37377614, 2023).
genetic diseases (1 paper, 2025). "Further studies are needed to investigate the possibility that CARM1 and METTL23 are involved in genetic diseases caused by lack of XPF activity and to approach anticancer drug resistance from the perspective of CARM1 and METTL23." (PMID 40304182, 2025).
infection (1 paper, 2025). The state of being infected such as from the introduction of a foreign agent such as serum, vaccine, antigenic substance or organism. "Western blot results showed that the protein levels of LEDGF or CARM1 were almost eliminated in ccRCC cells after infection with indicated lentivirus." (PMID 40548925, 2025).
skeletal muscle disorder (1 paper, 2025). A disease involving the skeletal muscle tissue. "In summary, as a pivotal hub linking epigenetic modifications to skeletal muscle function, CARM1 not only offers new insights into muscle physiology and pathology but also provides potential targets for developing personalized, precision intervention strategies for skeletal muscle disorders." (PMID 41488004, 2025).
CARM1 also shares sentences with these, for which no sentence is quoted: cardiomyopathy (4 papers); adenoma (2); brain tumors (2); esophageal cancer (2); hematopoietic cancer (2); lymph node metastasis (2); lymphoma (2); neuroblastoma (2); pancreatic adenocarcinoma (2); acute promyelocytic leukemia (1); bacterial infection (1); Burkitt lymphoma (1); cerebral infarction (1); cholangiocarcinoma (1); colon adenocarcinoma (1); congenital heart disease (1); diabetes (1); embryonal carcinoma (1); endocervical adenocarcinoma (1); epithelial ovarian cancer (1); esophageal squamous cell carcinoma (1); frontotemporal dementia (1); gastrointestinal tumors (1); head and neck squamous cell carcinoma (1); head and neck tumors (1); heart failure (1); herpes simplex infection (1); Huntington disease (1); Hyperglycemia (1); Hyperinsulinemia (1).
A further 25 diseases each share a sentence with CARM1 in 1 paper.